INS (insulin)
Diseases named in the same sentence as INS in open-access papers (continued):
Sharing a sentence is not in itself a finding about the gene and the disease.
Hypoglycemia (continued). "Earlier offset of exposure and glucose‐lowering effect with faster aspart versus IAsp might improve the balance between the glucose load from a meal and the exogenous insulin absorption during the late postprandial phase, leading to lower risk of late postprandial hypoglycaemia." (PMID 31069935, 2019). "Moreover, carvedilol use is associated with lower hypoglycemia symptom scores and a favorable metabolic profile compared to metoprolol, which may influence insulin requirements and hypoglycemia." (PMID 31775749, 2019). "Relatively tight HbA1c control in an older population may be of concern particularly for patients prescribed sulphonylureas and insulin as these medications are associated with increased risk of hypoglycaemia, which is associated with increased risk of cardiovascular events and death." (PMID 30777033, 2019). "In the Netherlands, use of medications like insulin, which is known to induce hypoglycemia on occasion, may lead to job loss (e.g., when driving a bus or a heavy lorry), which might be prevented when users show their ability to better control their blood glucose levels." (PMID 31781209, 2019). "Thirdly, insulin treatment and the associated risk of hypoglycaemia may also be relevant." (PMID 31271255, 2019). "Moreover, we observed that SST cells deficiency led to increased insulin content and excessive insulin release, which might contribute to the observed hypoglycemia." (PMID 29880854, 2018). "Because of concerns that intensifying insulin therapy in diabetic gastroparesis might cause hypoglycemia due to mismatches consequent to delayed nutrient absorption, our primary outcome was to compare combined weekly mild, moderate, and severe hypoglycemic episodes before and during CSII plus CGM." (PMID 29652893, 2018). "As demonstrated in a previous model-based simulation study (König and Holzhütter, 2012), exposing the permanently glucose-releasing “starved” liver of the diabetic patient to a rigorous insulin treatment at persistently elevated glucagon level may increase the risk of severe hypoglycaemia." (PMID 30631280, 2018). "In addition, our results also raise the possibility that there are some patients who are more susceptible to severe hypoglycaemia because they are unable or unwilling, for a variety of reasons, to appropriately modify their insulin dose to reduce their fasting glycaemic variability." (PMID 28913575, 2018). "Glyburide use has been approved in pregnancy; however, studies have shown some elevated risk of neonatal hypoglycemia compared to insulin, and increased expression of GLUT1 on the placenta which may facilitate higher nutrient transfer to the fetus and confer higher risk of macrosomia." (PMID 30400566, 2018). "Thus, hypoketonemic hypoglycemia induced by insulin injection or insulin secretagogue administration may be associated with a higher risk of cardiovascular events when compared with hyperketonemic hypoglycemia induced by starvation or SGLT2 inhibitor therapy." (PMID 29554103, 2018). "However, as time goes by and insulin treatment is prolonged over the years, the risk of hypoglycemia increases, and a basal insulin such as glargine may reduce the hypoglycemia risk as compared with NPH, even in this subgroup of obese people." (PMID 28151905, 2017). "However, meglitinide with insulin will increase the risk of hypoglycemia." (PMID 29100450, 2017). "Furthermore, advanced DKD patients have been found to be at greater risk of hypoglycemia in cases involving decreased degradation of insulin in peripheral tissue, anorexics with suboptimal nutrition, reduced renal gluconeogenesis, and prolonged half-life of antidiabetic drugs." (PMID 28355264, 2017). "In spite of careful planning and manipulation of subcutaneous insulin administration, increased risk of hypoglycaemia and glycaemic variability during and after exercise may occur as a result of inherent delays in insulin action and impaired counter-regulatory hormone responses." (PMID 27287376, 2016).
Hypoglycemia (continued). "However, insulin therapy is associated with the risk of hypoglycemia and weight gain." (PMID 27316668, 2016). "None of these studies was intended to describe adverse effects that might be observed during the test; rather, their aim was to investigate the likely causes of hypoglycemia by measuring related parameters, such as blood glucose, insulin, C-peptide and glucagon-like peptide type 1 (GLP-1)." (PMID 26910630, 2016). "As age, frailty, insulin treatment, and chronic kidney disease are known risk factors for hypoglycemia and hypoglycemic symptoms may be mistaken for other conditions associated more commonly with advanced ages, strategies to prevent hypoglycemia in very old patients should be emphasized." (PMID 27246619, 2016). "However, these agents can increase the risk of hypoglycemia when combined with sulfonylureas and insulin; hence, the sulfonylurea or insulin dose may need to be reduced." (PMID 27148163, 2016). "However, unfavorable perceptions regarding frequent and lifestyle impacting injections and the potential adverse effects associated with insulin usage, such as hypoglycemia, have limited the wider adoption of insulin products, and have consequently hindered better glycemic control in patients." (PMID 25799496, 2015). "In patients who received irradiation, insulin-induced hypoglycemia may be the most sensitive and reliable pharmacologic test of GH status, however because it carries the risk of serious hypoglycemia-related events, it should be performed only in experienced clinics under close surveillance." (PMID 26777035, 2015). "Moreover, previous antidiabetic agents, including insulin, were replaced with vildagliptin to avoid the risk of hypoglycemia, although vildagliptin in addition to previous drugs may be more effective." (PMID 26550558, 2015). "However, high doses of glucagon may paradoxically stimulate insulin secretion and increase glucose infusion requirements or cause further, rebound hypoglycaemia." (PMID 26316429, 2015). "However, insulin therapy may lead to weight gain, increasing risk of hypoglycemia, edema, and some other side effects." (PMID 26500706, 2015). "In addition, the intraday and day-to-day variability in insulin agents could sometimes be an obstacle for optimized titration of insulin and a cause of increased frequency of hypoglycemia." (PMID 26435713, 2015). "However, hypoglycemia due to other causes could also present refractory after modification of insulin dose and food intake." (PMID 25961056, 2015). "Furthermore, the time span between the insulin administration and exercise (a time span that led to the full impact of short-acting insulin) was unsuitable to investigate the exercise-induced BG decrease and the risk of hypoglycemia yielded by different exercise modes." (PMID 26317981, 2015). "However, both endogenous hyperinsulinaemia and exogenous insulin could increase the risk of atherosclerosis and cancer, meanwhile some physicians have concerns about hypoglycemia and weight gain with intensive insulin treatment." (PMID 24650537, 2014). "A recent meta-analysis compiling trials that compared intensive management (using insulin) with standard treatment found a small benefit in the intensive therapy group concerning non-fatal myocardial infarction and microalbuminuria, which was offset by a significant risk of severe hypoglycaemia." (PMID 24752580, 2014). "However, whether the occurrence of recurring episodes of insulin-induced hypoglycemia could cause permanent cognitive alterations is still unknown." (PMID 24790575, 2014). "Therefore, it is necessary to analyze each case carefully, aiming at establishing the participation of factors related to hypoglycemia in the development of cognitive deficit, especially in children submitted to insulin therapy, since they are more susceptible to hypoglycemia." (PMID 24790575, 2014).
Hypoglycemia (continued). "Thus, the use of insulin secretagogues may be limited because of an increase in beta cell workload as well as increased risk of hypoglycemia." (PMID 26237486, 2014). "The observational study shows that, in T2DM patients inadequately controlled with premixed insulin, switching therapy to glargine plus OADs is associated with significant improvements in glycaemic control and treatment satisfaction, and is with low incidence of hypoglycemia." (PMID 24620742, 2014). "Furthermore, the risk of hypoglycemia is strongly dependent on the choice of insulin." (PMID 23574917, 2013). "Although there is some evidence to support a CV protective role for insulin treatment there are many studies indicating that insulin might be a double-edged sword with regard to CV health because of its associated risk of inducing hypoglycaemia." (PMID 24053606, 2013). "Reasons for the difficulty in achieving target HbA1c levels may include problems adhering to complex oral and injectable therapies, concerns about insulin tolerability, psychological insulin resistance, fears about the risk of hypoglycaemia, and weight gain after insulin initiation." (PMID 24228724, 2013). "In the case of T2D, hypoglycaemia may be less frequent, and usually results from the use of drugs that cause increased endogenous insulin levels (e.g. sulfonylureas) or treatment with exogenous insulin." (PMID 24053606, 2013). "However, intensive insulin therapy may be associated with an increase in adverse effects, particularly hypoglycemia and weight gain 2–6." (PMID 23448369, 2013). "In summary, the risk of cancer potentially associated with insulin therapy, if present at all, should be considered irrelevant in comparison with the benefits of improved glycemic control and the other burdens of insulin treatment (most notably, hypoglycemia and weight gain)." (PMID 23209929, 2012). "However, insulin treatment is commonly associated with hypoglycemia and weight gain." (PMID 23153177, 2012). "The combination of exenatide with insulin has been shown to have an insulin-sparing effect in insulin-treated patients with T2D as well as a weight loss benefit in several small uncontrolled studies, furthermore, these studies reported a low incidence of severe hypoglycemia." (PMID 23153177, 2012). "However, higher CRE level might influence the insulin metabolism and degradation in patients and therefore might lead to higher risk of hypoglycemia." (PMID 22720003, 2012). "Additionally, in occasional patients, this may stimulate an exaggerated secretion of insulin, leading to postprandial hypoglycemia and associated signs and symptoms of neuroglycopenia." (PMID 22937294, 2012). "Further dissection of BAD as a molecular modulator of brain glucose sensing and its potential functional collaboration with other known glucose sensors may uncover novel insights as well as new therapeutic targets for the control of hypoglycemia caused by aggressive insulin therapy." (PMID 22162752, 2011). "The lower risk of hypoglycaemia with sitagliptin relative to sulphonylureas overall is consistent with the glucose-dependent actions of DPP-4 inhibitors relative to the non-glucose-dependent mechanism of action of potassium channel-based insulin secretagogues, such as sulphonylureas." (PMID 21951832, 2011). "Additionally, insulin, typically reserved for patients with poor glucose control, may be associated with a higher risk of hypoglycaemia, especially at nights and this may also interfere with sleeping patterns in patients concerned about this risk." (PMID 22164161, 2011). "Rapid-acting insulin analogues (lispro, aspart and glulisine) may be preferred over regular human insulin, as they have been associated with greater improvements in HbA1c with reduced risk of hypoglycaemia." (PMID 20456170, 2010).
Hypoglycemia (continued). "However, the use of insulin is associated with weight gain (2-4 kg), probably related to glycemic level correction and subsequent reduction in glycosuria, and increased risk of hypoglycemia, due to high glycemic control intensification, targeting HbA1c levels lower than 7%." (PMID 20718958, 2010). "Hypoglycemia incidence ranged from 5.0% to 18.7% in tight glucose target groups, and found a significantly increased overall risk of hypoglycemia (13.7% vs. 2.5%; relative risk 5.13; 95% confidence interval 4.10 to 6.43) with insulin treatment to lower glycemic targets." (PMID 19822000, 2009). "However, at a similar level of glycaemic control, a long-acting insulin analogue is associated with a lower risk of hypoglycaemia than NPH insulin in patients taking metformin and patients may prefer the convenience of a once-daily basal regimen." (PMID 19143853, 2008). "Indeed, insulin can be used as a diagnostic challenge test; however, the glucose-insulin challenge test is discouraged due to risk of both profound paralysis and life-threatening hypoglycemia." (PMID 18426576, 2008). "However, insulin glargine was associated with less nocturnal hypoglycemia than NPH insulin." (PMID 18279520, 2008). "In addition, there may be enhanced sensitivity to insulin, and sleep per se is associated with a decrease in the autonomic response to hypoglycemia." (PMID 17326722, 2007). "The turnaround time for glucose determinations by the central hospital laboratory was 30 to 60 minutes, which is too long for fast adjustment of the insulin infusion dose or other therapeutic actions as required in a glucose regulation protocol and might cause excess hypoglycaemia." (PMID 16981981, 2006). "Among patients with pre-existing hypoglycaemia, glycaemic control remained stable despite reductions in insulin dose and injection frequency (p = 0.001, p = 0.032, respectively)." (PMID 41919486, 2026). "The 1.2-U/kg insulin dose was one-third of the mean daily insulin maintenance dosage and lower than doses previously reported to induce hypoglycemia in this model (6-12 U/kg)." (PMID 41502124, 2026). "Careful timing of protein ingestion, and consideration of the dose consumed, have implications for preserving insulin sensitivity and reducing hypoglycemia during and after exercise." (PMID 41602572, 2026). "Despite good maternal glycemic control and relatively low insulin requirements, the infant was macrosomic and developed persistent postnatal hypoglycemia requiring prolonged diazoxide therapy." (PMID 42064724, 2026). "Machine-learning models fed with clinical, physiological, metabolomic, and behavioral data can forecast hypoglycemia, automate insulin titration, and predict chronic complications up to a decade in advance." (PMID 41596449, 2026). "Conversely, in an extensive study in mice, GLP-2 was unable to stimulate glucagon secretion from perfused pancreatic islets in vitro or during insulin-induced hypoglycemia in vivo." (PMID 41541287, 2026). "A total of 62 subjects undergoing growth hormone function tests were retrospectively enrolled and stratified by stimulation type: levodopa (n=28), insulin-induced hypoglycemia (n=7), glucagon (n=20), and octreotide (n=7)." (PMID 41814904, 2026). "Following optimization of glucose administration, intravenous short-acting regular human insulin was initiated with hourly glucose monitoring and complicated by early asymptomatic hypoglycemia requiring rapid correction and insulin dose reduction." (PMID 42051816, 2026). "Given the combination of severe hypoglycemia, markedly elevated insulin, normal C-peptide, and high insulin autoantibodies, a diagnosis of Insulin Autoimmune Syndrome (IAS) was confirmed." (PMID 41589093, 2026). "CGM is widely used for tracking glycemic levels during insulin treatment, proving valuable for insulin dose adjustments and hypoglycemia detection in these patients." (PMID 41552835, 2026).
Hypoglycemia (continued). "Hypoglycemia occurs not only due to excess insulin exposure, but also because of a failure of the counterregulatory processes that normally regulate falling blood glucose levels." (PMID 41502124, 2026). "Iatrogenic hypoglycemia in CFRD: Insulin treatment in CFRD improves nutritional status and pulmonary function but carries a risk of iatrogenic hypoglycemia." (PMID 41552835, 2026). "Other possible causes of hypoglycemia include critical illness, postbariatric hypoglycemia, alcohol abuse, adrenal insufficiency, and inappropriate use of insulin secretagogues." (PMID 41356535, 2026). "BsAUC for insulin during insulin-induced hypoglycemia was slightly but significantly lower during GLP-2 infusion compared to placebo (28.8 ± 2.8 [placebo] vs 24.4 ± 4.1 nmol/L × min [GLP-2]; P < .005)." (PMID 41541287, 2026). "We report the case of a 48-year-old female with long-standing T1D and ESKD who suffered from severe glycemic variability and recurrent hypoglycemia despite intensive insulin management." (PMID 42232681, 2026). "Total insulin dose and injection frequency significantly decreased (p < 0.001), while hypoglycaemia incidence dropped from 60.0% to 12.5% (p < 0.001)." (PMID 41919486, 2026). "Hypoglycemia—defined as BGLs below 70 mg/dL (3.9 mmol/L) in individuals receiving glucose‐lowering treatments such as insulin—is an important concern in PwCF." (PMID 41552835, 2026). "Hypoglycaemia leading to an insulin dose reduction was revealed by CGM in 91/177 participants (51.4%)." (PMID 41254466, 2026). "In 91 of 177 individuals (51.4%), CGM identified episodes of hypoglycaemia that led to a reduction in total daily dose of insulin (including both simple dose reductions and regimen changes)." (PMID 41254466, 2026). "CHI is a genetic disorder characterized by insulin hypersecretion and resultant hypoglycemia that often develops during infancy." (PMID 41347115, 2026). "HbA1c levels, body weight, insulin doses, and hypoglycemia rates were evaluated at baseline and up to 24 months." (PMID 42123262, 2026). "Insulin Autoimmune Syndrome (IAS) is a rare autoimmune condition in which the body produces antibodies to insulin, leading to recurrent episodes of severe hypoglycemia accompanied by elevated serum insulin and insulin antibody levels." (PMID 41755959, 2026). "This study also evaluated SSTR2a in conjunction with small and large insulin dosages, covering a 10-fold range up to 12 U/kg, sufficient to induce hypoglycemia in all vehicle-treated (ie, control) rats." (PMID 41502124, 2026). "As a result, HT can promote recurrent episodes of hypoglycemia and heightened glucose variability, requiring less insulin for T1D." (PMID 41317333, 2026). "This is followed by unpredictable dissociation several hours later, resulting in a sudden surge of free insulin at a time when glucose levels are already falling, which can lead to severe hypoglycemia." (PMID 41589093, 2026). "The analysis demonstrated a similar glucose‐lowering effect compared to once‐daily basal insulin but revealed an increased occurrence of severe hypoglycaemia." (PMID 41048193, 2026). "Impaired Awareness of Hypoglycemia (IAH) describes a condition in insulin-treated diabetic patients characterized by a diminished ability to perceive the onset of acute hypoglycemia." (PMID 41907548, 2026). "At the time of hypoglycemia, the patient’s insulin level was 196 mIU/L (ADVIA Centaur; Siemens) and C peptide was undetectable (e602 Cobas, Roche)." (PMID 41472947, 2026). "In low-resource settings, IGlar can be a cost-effective alternative to NPH, largely due to reduced nocturnal hypoglycemia, but the delivery device for the insulin has a major impact on the costs and cost-effectiveness comparisons." (PMID 41481625, 2026). "Although approximately one third of recipients achieve insulin independence, spontaneous hypoglycemia has been observed in this population." (PMID 42053924, 2026).